SNORA2A (small nucleolar RNA, H/ACA box 2A)
Synonyms: ACA2A
Gene: Small nucleolar RNA gene on chromosome 12 (48,656,648 to 48,656,782, reverse strand). Ensembl gene ENSG00000206612.
Gene Ontology:
Biological process: RNA processing
Cellular component: nucleolus
Homologues: Orthologues: macaque SNORA2A (99% identical), chimpanzee SNORA2A (99% identical). Paralogues in human: SNORA2B (75% identical), SNORA2C (73% identical).